ZNF329 (zinc finger protein 329)
Description:
May be involved in transcriptional regulation.
Synonyms: FLJ12586
Tractability: PROTAC: ubiquitination databases record sites on it.
Gene: Protein-coding gene on chromosome 19 (58,126,248 to 58,155,110, reverse strand). Ensembl gene ENSG00000181894.
Subcellular location: Nucleus
Subcellular location (Human Protein Atlas): Nucleoplasm
Gene Ontology:
Molecular function: protein binding; DNA-binding transcription activator activity, RNA polymerase II-specific; DNA-binding transcription factor activity; RNA polymerase II cis-regulatory region sequence-specific DNA binding; sequence-specific double-stranded DNA binding
Biological process: regulation of transcription by RNA polymerase II; positive regulation of transcription by RNA polymerase II
Cellular component: nucleus
Genetic constraint (gnomAD): Loss-of-function variants: 21 observed, 34.69 expected, observed/expected ratio (o/e) 0.61, 90% interval 0.43 to 0.87. The upper end of that interval is the gene's LOEUF score, 0.87, which puts it in group 3 of 6, group 1 being the genes least tolerant of losing a copy. Missense variants: 651 observed, 683.8 expected, observed/expected ratio (o/e) 0.95, 90% interval 0.89 to 1.02. Synonymous variants: 239 observed, 244.97 expected, observed/expected ratio (o/e) 0.98, 90% interval 0.88 to 1.09.
Homologues: Orthologues: chimpanzee ZNF329 (99% identical), macaque ZNF329 (96% identical), pig ZNF329 (83% identical), dog ZNF329 (83% identical), rabbit ZNF329 (78% identical), rat Zfp329 (73% identical), mouse Zfp329 (71% identical), Drosophila melanogaster CG3281 (17% identical), Drosophila melanogaster CG2712 (15% identical), Drosophila melanogaster Phs (14% identical). Paralogues in human: ZNF10 (35% identical), ZFP37 (32% identical), ZNF555 (32% identical), ZFP90 (30% identical), ZNF35 (30% identical), ZNF266 (30% identical), ZNF749 (30% identical), ZNF180 (29% identical), ZNF674 (29% identical), ZNF805 (29% identical), ZNF599 (29% identical), ZNF264 (28% identical), and 50 more.
Diseases named in the same sentence as ZNF329 in open-access papers:
ZNF329 is named in the same sentence as 2 diseases in open-access papers, as found by Europe PMC text mining. Sharing a sentence is not in itself a finding about the gene and the disease. The quoted sentences say what the papers report.
brain tumors (1 paper, 2016). "The relationship between ZNF329 and brain tumors is still unclear, but zinc finger protein family has been proved to be associated with brain tumor." (PMID 27556418, 2016). "For another real expression data from the patients affected by human brain tumors, CBDN predicts two potential important regulators ZNF329 and RB1 whose function are associated with brain tumors." (PMID 27556418, 2016). "ZNF329 and RB1 significantly regulate those ‘mesenchymal’ gene expression signature genes for brain tumors." (PMID 27556418, 2016).
cancer (1 paper, 2021). A tumor composed of atypical neoplastic, often pleomorphic cells that invade other tissues. "Finally, OV_sBRCA2 was characterized by the up-regulation of zinc finger proteins (ZNF613, ZNF329, ZNF530, ZNF347), a gene family known to be involved in pathways of carcinogenesis, cancer progression, and metastasis formation." (PMID 33525353, 2021).